PLK1 (polo like kinase 1)
Description:
Serine/threonine-protein kinase that performs several important functions throughout M phase of the cell cycle, including the regulation of centrosome maturation and spindle assembly, the removal of cohesins from chromosome arms, the inactivation of anaphase-promoting complex/cyclosome (APC/C) inhibitors, and the regulation of mitotic exit and cytokinesis. Polo-like kinase proteins act by binding and phosphorylating proteins that are already phosphorylated on a specific motif recognized by the POLO box domains. Phosphorylates BORA, BUB1B/BUBR1, CCNB1, CDC25C, CEP55, ECT2, ERCC6L, FBXO5/EMI1, FOXM1, KIF20A/MKLP2, CENPU, NEDD1, NINL, NPM1, NUDC, PKMYT1/MYT1, KIZ, MRE11, PPP1R12A/MYPT1, POLQ, PRC1, RACGAP1/CYK4, RAD51, RHNO1, SGO1, STAG2/SA2, TEX14, TOPORS, p73/TP73, TPT1, WEE1 and HNRNPU. Plays a key role in centrosome functions and the assembly of bipolar spindles by phosphorylating KIZ, NEDD1 and NINL. NEDD1 phosphorylation promotes subsequent targeting of the gamma-tubulin ring complex (gTuRC) to the centrosome, an important step for spindle formation. Phosphorylation of NINL component of the centrosome leads to NINL dissociation from other centrosomal proteins. Involved in mitosis exit and cytokinesis by phosphorylating CEP55, ECT2, KIF20A/MKLP2, CENPU, PRC1 and RACGAP1. Recruited at the central spindle by phosphorylating and docking PRC1 and KIF20A/MKLP2; creates its own docking sites on PRC1 and KIF20A/MKLP2 by mediating phosphorylation of sites subsequently recognized by the POLO box domains. Phosphorylates RACGAP1, thereby creating a docking site for the Rho GTP exchange factor ECT2 that is essential for the cleavage furrow formation. Promotes the central spindle recruitment of ECT2. Plays a central role in G2/M transition of mitotic cell cycle by phosphorylating CCNB1, CDC25C, FOXM1, CENPU, PKMYT1/MYT1, PPP1R12A/MYPT1 and WEE1. Part of a regulatory circuit that promotes the activation of CDK1 by phosphorylating the positive regulator CDC25C and inhibiting the negative regulators WEE1 and PKMYT1/MYT1. Also acts by mediating phosphorylation of cyclin-B1 (CCNB1) on centrosomes in prophase. Phosphorylates FOXM1, a key mitotic transcription regulator, leading to enhance FOXM1 transcriptional activity. Involved in kinetochore functions and sister chromatid cohesion by phosphorylating BUB1B/BUBR1, FBXO5/EMI1 and STAG2/SA2. PLK1 is high on non-attached kinetochores suggesting a role of PLK1 in kinetochore attachment or in spindle assembly checkpoint (SAC) regulation. Required for kinetochore localization of BUB1B. Regulates the dissociation of cohesin from chromosomes by phosphorylating cohesin subunits such as STAG2/SA2 (By similarity). Phosphorylates SGO1: required for spindle pole localization of isoform 3 of SGO1 and plays a role in regulating its centriole cohesion function. Mediates phosphorylation of FBXO5/EMI1, a negative regulator of the APC/C complex during prophase, leading to FBXO5/EMI1 ubiquitination and degradation by the proteasome. Phosphorylates the transactivation domain of the transcription factor p73/TP73, leading to inhibit p73/TP73-mediated transcriptional activation and pro-apoptotic functions. Phosphorylates BORA, and thereby promotes the degradation of BORA. Contributes to the regulation of AURKA function. Also required for recovery after DNA damage checkpoint and entry into mitosis. Phosphorylates MISP, leading to stabilization of cortical and astral microtubule attachments required for proper spindle positioning. Together with MEIKIN, acts as a regulator of kinetochore function during meiosis I: required both for mono-orientation of kinetochores on sister chromosomes and protection of centromeric cohesin from separase-mediated cleavage (By similarity). Phosphorylates CEP68 and is required for its degradation. Regulates nuclear envelope breakdown during prophase by phosphorylating DCTN1 resulting in its localization in the nuclear envelope. Phosphorylates the heat shock transcription factor HSF1, promoting HSF1 nuclear translocation upon heat shock. Phosphorylates HSF1 also in the early mitotic period; this phosphorylation regulates HSF1 localization to the spindle pole, the recruitment of the SCF(BTRC) ubiquitin ligase complex induicing HSF1 degradation, and hence mitotic progression. Regulates mitotic progression by phosphorylating RIOK2. Through the phosphorylation of DZIP1 regulates the localization during mitosis of the BBSome, a ciliary protein complex involved in cilium biogenesis. Regulates DNA repair during mitosis by mediating phosphorylation of POLQ and RHNO1, thereby promoting POLQ recruitment to DNA damage sites. Phosphorylates ATXN10 which may play a role in the regulation of cytokinesis and may stimulate the proteasome-mediated degradation of ATXN10.
Synonyms: STPK13; PLK
Tractability: Small molecule: a drug acting on it is in phase 2 or 3 trials; a structure with a bound ligand is known; a high-quality ligand is known; it has a high-quality binding pocket; it belongs to a druggable protein family. PROTAC: it is named in the literature on targeted protein degradation; UniProt records ubiquitination sites on it; ubiquitination databases record sites on it; a small molecule that binds it is known.
Target class: Other protein kinase PLK family; Kinase; Enzyme; Protein Kinase; Other protein kinase group
Chemical probes: BI 2536 (high quality), CHEMBL3609300, CYCLAPOLIN 1, GSK 461364 analogue II, GSK317314A, GSK317315A, GSK326090A, GSK483724A, GSK571989A, GSK579289A (high quality), GSK641502A, GSK907232A, GSK978744A, ML043, Onvansertib, PD080746, PD080861, PD081249, PD081275, PD081285, and 54 more
Safety:
Unwanted effects reported when the protein is acted on. In parentheses: how it was acted on, where the effect was seen, and who reports it.
heart disease (cardiovascular system; source: Force et al. (2011))
Gene: Protein-coding gene on chromosome 16 (23,677,656 to 23,690,367, forward strand). Ensembl gene ENSG00000166851.
Subcellular location: Nucleus; Chromosome, centromere, kinetochore; Cytoplasm, cytoskeleton, microtubule organizing center, centrosome; Cytoplasm, cytoskeleton, spindle; Midbody
Pathways (Reactome):
Cell Cycle: APC/C:Cdh1 mediated degradation of Cdc20 and other APC/C:Cdh1 targeted proteins in late mitosis/early G1; AURKA Activation by TPX2; Activation of NIMA Kinases NEK9, NEK6, NEK7; Amplification of signal from unattached kinetochores via a MAD2 inhibitory signal; Condensation of Prophase Chromosomes; Cyclin A/B1/B2 associated events during G2/M transition; EML4 and NUDC in mitotic spindle formation; Golgi Cisternae Pericentriolar Stack Reorganization; Loss of Nlp from mitotic centrosomes; Loss of proteins required for interphase microtubule organization from the centrosome; Mitotic Metaphase/Anaphase Transition; Mitotic Prometaphase; Mitotic Telophase/Cytokinesis; Phosphorylation of Emi1; Phosphorylation of the APC/C; Polo-like kinase mediated events; Recruitment of NuMA to mitotic centrosomes; Recruitment of mitotic centrosome proteins and complexes; Regulation of PLK1 Activity at G2/M Transition; Resolution of Sister Chromatid Cohesion; Separation of Sister Chromatids; The role of GTSE1 in G2/M progression after G2 checkpoint
Developmental Biology: Regulation of MITF-M-dependent genes involved in cell cycle and proliferation
Organelle biogenesis and maintenance: Anchoring of the basal body to the plasma membrane
Signal Transduction: RHO GTPases Activate Formins
Gene Ontology:
Molecular function: anaphase-promoting complex binding; ATP binding; identical protein binding; magnesium ion binding; microtubule binding; protein binding; protein kinase activity; protein kinase binding; protein serine kinase activity; protein serine/threonine kinase activity
Biological process: astral microtubule organization; centrosome cycle; double-strand break repair; double-strand break repair via alternative nonhomologous end joining; establishment of protein localization; G2/M transition of mitotic cell cycle; microtubule bundle formation; mitotic cell cycle; mitotic cleavage furrow formation; mitotic cytokinesis; mitotic G2 DNA damage checkpoint signaling; mitotic sister chromatid segregation; mitotic spindle assembly checkpoint signaling; negative regulation of apoptotic process; negative regulation of double-strand break repair via homologous recombination; negative regulation of transcription by RNA polymerase II; positive regulation of mitotic metaphase/anaphase transition; positive regulation of mitotic nuclear envelope disassembly; positive regulation of proteasomal ubiquitin-dependent protein catabolic process; positive regulation of ubiquitin-dependent protein catabolic process; protein localization to chromatin; protein phosphorylation; regulation of cytokinesis; regulation of mitotic cell cycle; regulation of mitotic metaphase/anaphase transition; and 14 more
Cellular component: centrosome; kinetochore; microtubule cytoskeleton; midbody; nucleus; outer kinetochore; spindle; spindle microtubule; spindle midzone; spindle pole; cytoplasm; cytosol; nucleoplasm; centriolar satellite; centriole; chromatin; chromosome, centromeric region; condensed chromosome, centromeric region; mitotic spindle pole; synaptonemal complex
Genetic constraint (gnomAD): Loss-of-function variants: 5 observed, 51.17 expected, observed/expected ratio (o/e) 0.0977, 90% interval 0.05 to 0.2. The upper end of that interval is the gene's LOEUF score, 0.2, which puts it in group 1 of 6, group 1 being the genes least tolerant of losing a copy. Missense variants: 529 observed, 804.46 expected, observed/expected ratio (o/e) 0.66, 90% interval 0.61 to 0.71. Synonymous variants: 285 observed, 318.51 expected, observed/expected ratio (o/e) 0.89, 90% interval 0.81 to 0.99.
Homologues: Orthologues: macaque PLK1 (99% identical), rabbit PLK1 (98% identical), pig PLK1 (97% identical), dog PLK1 (96% identical), rat Plk1 (95% identical), mouse Plk1 (95% identical), guinea pig PLK1 (94% identical), chimpanzee PLK1 (92% identical), tropical clawed frog plk1 (78% identical), Drosophila melanogaster polo (50% identical). Paralogues in human: PLK3 (41% identical), PLK2 (39% identical), PLK4 (26% identical), PLK5 (15% identical).
Diseases named in the same sentence as PLK1 in open-access papers:
PLK1 is named in the same sentence as 267 diseases in open-access papers, as found by Europe PMC text mining. Sharing a sentence is not in itself a finding about the gene and the disease. The quoted sentences say what the papers report.
breast carcinoma (229 papers, 2005 to 2025). "PLK1 knockdown in hormone-independent ER+ breast cancer has been associated with decreased cell viability and sensitization to radiation treatment." (PMID 39057065, 2024). "Meta-analysis findings suggest that PLK1 serves as a risk factor for breast cancer (p = 0.28, I2 = 22%)." (PMID 39596658, 2024). "Further analysis using in silico techniques revealed that the anti-breast cancer activity of L-ZnONPs was linked to the regulation of polo-like kinase 1 (PLK1) proteins." (PMID 38474604, 2024). "Regarding the mechanisms underlying the tumor suppressive effects of SAMD5, PLK1 has been found to be negatively correlated with SAMD5 in breast cancer." (PMID 39524172, 2024). "The serine/threonine protein kinase polo-like kinase 1 (PLK1) is found to be overexpressed in breast cancer and has been associated with poor prognosis." (PMID 39409880, 2024). "In general, the overexpression of PLK1 has been associated with various cancer types, including ER+ breast cancer." (PMID 39057065, 2024). "In the clinic, high PLK1 levels have been associated with resistance to cyclin-dependent kinase 4/6-targeted therapy in luminal breast cancer, and to estrogen-targeted therapy." (PMID 39513002, 2024). "PLK1 is overexpressed in various human cancers, including melanoma, prostate cancer, colorectal cancer, hepatocellular carcinoma, and breast cancer, and its expression is associated with enhanced cell proliferation and poor prognosis in patients with cancer." (PMID 38355643, 2024). "As indicated in prior research, PLK1 exhibits an association with unfavorable prognosis of patients in breast cancer, hepatocellular carcinoma, colorectal cancer, synovial sarcoma, lung adenocarcinoma and various other malignancies." (PMID 38037110, 2023). "GSEA showed that retinoblastoma, PLK1 pathway, cell cycle checkpoints, and mitotic spindle checkpoint were significantly enriched in high-risk breast cancer." (PMID 36936412, 2023). "In breast cancer, PLK-1 was significantly associated with 5-year overall survival, histological grade, and lymph node metastasis (p < 0.001, p = 0.003, p < 0.001, respectively)." (PMID 36457496, 2022). "PLK1 has been widely considered both a novel diagnostic marker and a proto-oncogene for several tumor types, including breast cancer." (PMID 34561554, 2022). "In patients, the expression of PLK1 is positively associated with good prognosis in specific breast cancer subtypes." (PMID 34775484, 2022). "Due to its fundamental role in cell cycle regulation, PLK1 has been linked to various types of cancer onset and progression, such as lung, colon, prostate, ovary, breast cancer, melanoma, and AML." (PMID 36297281, 2022). "Especially, overexpression of CCNB1 and PLK1 are strongly associated with the low survival rate of breast cancer patients, demonstrating their potentiality as prognostic markers." (PMID 35456460, 2022). "For example, PLK1, a substrate of TRiC, is overexpressed in breast cancer and is considered as a diagnostic prediction model." (PMID 36239351, 2022). "For some human malignancies such as breast cancer, elevated PLK1 levels are beneficial and associated with better prognosis though reduced levels have also been reported to be exacerbating in this cancer entity." (PMID 34065956, 2021). "Aberrant expression of Plk-1 is strongly associated with development of many types of cancer including breast cancers and is related to a poor clinical prognosis." (PMID 31454976, 2019). "The second paper published in 2015 described the use of an EpCAM aptamer linked to a PlK-1 siRNA for the treatment of breast cancer." (PMID 28792479, 2017).
breast carcinoma (continued). "CQ-mediated cell-cycle-arrest and apoptosis was observed in breast cancer cells and was associated with a decrease in protein levels/activity of polo-like kinase 1 (Plk-1), ERK1/2 Akt and cell division cycle 25C (CDC25C)." (PMID 29225688, 2017). "We found that two linker genes COL4A6 (p = 0.01) and PLK1 (p = 0.07) whose expressions are weakly associated with the survival of breast cancer patients." (PMID 25137136, 2014). "Most important, our study represents the first attempt to associate PLK1 with TICs in breast cancer." (PMID 22309939, 2012). "Additionally, CCNB2 has been linked to metastasis in nasopharyngeal cancer, breast cancer, and non-small-cell lung cancer; PLK1 in pancreatic cancer and melanoma; and CCNB1 in esophageal cancer." (PMID 40076867, 2025). "Moreover, elevated levels of CCNB1 and PLK-1 are known to be strongly associated with low overall survival in other solid tumors like breast cancer, demonstrating their potentiality as prognostic markers and as combinatorial drug targets." (PMID 39684470, 2024). "Moreover, a recent study reported that elevated levels of PLK1 mRNA were associated with poorer response to palbociclib plus ET in HR+ breast cancer patients." (PMID 39409880, 2024). "Additionally, PLK1 has emerged as a potential blood-based diagnostic marker for breast cancer patients." (PMID 39596658, 2024). "Furthermore, there is evidence that PLK1 regulates the transcription of ER in human breast cancer cells, and is associated with the prognosis and survival of BRCA patients." (PMID 38186570, 2023). "The PLK1‐based immune risk model could accurately identify immunotherapy‐or chemotherapy‐sensitive breast cancer patients, which is expected to act as a biomarker for personalized BC treatment." (PMID 36951624, 2023). "Thus, in the human population, variation in the enhancer region of PLK1 appears to specifically modify breast cancer risk for BRCA1 mutation carriers." (PMID 35459234, 2022). "Therefore, it is not surprising that PLK1 expression is increased in various human malignant tumors, such as breast cancer, colorectal cancer, and melanoma, and PLK1 upregulation is associated with the poor prognosis of cancer patients." (PMID 34869364, 2021). "In addition, emerging evidence suggests that the Fbw7-PLK1 axis regulates the response to paclitaxel because loss of Fbw7 and accumulation of PLK1 promote paclitaxel resistance in breast cancer." (PMID 34503223, 2021). "Importantly, increased levels of Plk1 in breast cancer patients is associated with better prognosis." (PMID 30069007, 2018). "Similarly, the mitotic kinase PLK1 is also overexpressed in various cancer tissues, including breast cancer, and frequently associated with poor prognosis." (PMID 29976159, 2018). "Notably, for the first time, we observed a direct association between FBXW7 and PLK1 expression in breast cancer tissues." (PMID 27409838, 2016). "PLK1 is a highly conserved serine/threonine protein kinase with important regulatory mitotic effects whose high expression levels have been significantly associated with abnormal tumor cell proliferation, metastasis, angiogenesis, and tumor prognosis in various cancers such as breast cancer." (PMID 34723284, 2021). "PLK1, critical for mitosis, is also overexpressed in aggressive breast cancers, correlating with poor prognosis." (PMID 40081286, 2025).